SOCS3 (suppressor of cytokine signaling 3)
Diseases named in the same sentence as SOCS3 in open-access papers (continued):
Sharing a sentence is not in itself a finding about the gene and the disease.
colitis (continued). "Together, these results demonstrate that miR-19b significantly decreased inflammation in TNBS-induced colitis, which may be due to miR-19b’s targeted regulation of SOCS3." (PMID 25997679, 2015). "However, SOCS3 protein in TNBS-induced colitis was decreased after intra-colonic administration with pre-miR-19b." (PMID 25997679, 2015). "Furthermore, the expression of SOCS3 was inhibited in TNBS-induced colitis model after treatment with pre-miR-19b." (PMID 25997679, 2015). "Moreover, it downregulated the expression of SOCS3 in a DSS-induced colitis model." (PMID 34594215, 2021). "Similar outcomes indicated the ability of GAL to abate the expression of JAK/STAT3 in a model of colitis, high-fat diet, and AKI while improving SOCS3 expression in inflammatory bowel disease." (PMID 37429998, 2024). "Overall, these studies demonstrate that deletion of Socs3 in myeloid cells contributes to hyper-activation and enhanced inflammation, leading us to postulate that Socs3-deficient myeloid cells may play a potential role in the pathogenesis of DSS-induced colitis." (PMID 37283760, 2023). "For example, histone 3 lys27 tri-methyltransferase Ezh2 epigenetically inhibited antiinflammatory mediator Socs3 in macrophages by mediating H3K27me3, which promoted autoimmune inflammation in DSS-induced colitis and experimental autoimmune encephalomyelitis." (PMID 37733446, 2023). "In mice, activation of STAT3 and expression of SOCS3 is characteristic for the development of IBD and colitis, with SOCS3 acting as a regulatory mechanism to limit pathogenesis, which is primarily driven through macrophages." (PMID 34604264, 2021). "Together, these results suggest that miR-19b regulates SOCS3 protein expression and MIP-3α expression in TNBS-induced colitis." (PMID 25997679, 2015). "We also found that miR-19b expression was decreased, while SOCS3 expression was increased, in TNBS-induced colitis, and this finding is similar to that seen in CD patients." (PMID 25997679, 2015). "To investigate the relationship between miR-19b and SOCS3 in the pathogenesis of colitis, we employed the TNBS-induced colitis model and examined SOCS3 expression after intra-colonic pre-miR-19b, pre-scramble or 50% ethanol administration." (PMID 25997679, 2015). "Overall, our findings demonstrate the importance of Socs3 in repressing the hyper-activation of myeloid cells, specifically neutrophils, which contribute to our understanding of the role of neutrophils in IBD/colitis." (PMID 37283760, 2023). "have documented that EZH2 deficiency suppressed M1 polarization and attenuated the inflammatory responses through the SOCS3/STAT1 pathway, leading to the suppression of autoimmune inflammation diseases including DSS-induced colitis in an experimental autoimmune encephalomyelitis (EAE) model." (PMID 35432300, 2022). "In addition, SOCS3, a negative regulator of the JAK2 signal pathway, is upregulated as result of the aggravation of the JAK2 signal pathway in patients diagnosed with colitis." (PMID 34594215, 2021). "A 16-gene signature (CARD12, CCL3, CCR3, CXCL1, F5, FAM210B, GADD45A, IL18bp, IL2RA, IL5, IL8, MMP9, PTGS2, SOCS3, TLR9 and UBE2C) was identified from 30 days post-tremelimumab initiation blood that discriminated patients developing grade 0–1 from grade 2–4 diarrhea/colitis." (PMID 30227886, 2018). "Our results from miRNA in situ hybridization show that miR-19b is expressed in both IECs and non-epithelial cells in intestinal tissue; thus, both epithelial and non-epithelial miR-19b-SOCS3 signals may be important for colitis development." (PMID 25997679, 2015).
psoriasis (17 papers, 2010 to 2025). An autoimmune condition characterized by red, well-delineated plaques with silvery scales that are usually on the extensor surfaces and scalp. "Dysregulation of SOCS3 has been associated with various inflammatory conditions, including rheumatoid arthritis, inflammatory bowel disease, and psoriasis." (PMID 38975347, 2024). "Keratinocyte‐specific deletion of SOCS3 was found to cause psoriasis‐like skin inflammation with keratinocyte, immunoglobulin E (IgE) hyperproduction, and antimicrobial peptide expression in mice." (PMID 36169255, 2022). "In psoriasis, SOCS3 and SOCS1 suppress cytokine-induced apoptosis by sustaining the activation of the PI3K/AKT pathway in keratinocytes." (PMID 38975347, 2024). "IFN-γ/TNF-α-treated keratinocytes of psoriasis patients strongly express SOCS3 and SOCS1, at higher levels as compared to healthy cells." (PMID 38975347, 2024). "SOCS3 expression levels have been found to be much lower in T cells from patients with psoriasis compared with T cells from healthy donors." (PMID 36169255, 2022). "The deregulated IL‐6/STAT3/SOCS3 axis promoted keratinocyte proliferation, leading to the development of a severe clinical phenotype that resembled psoriasis in these transgenic mice." (PMID 36169255, 2022). "Few studies in the literature have examined the interactions between SOCS3 and SOCS7 gene polymorphisms and immune diseases, and more studies are needed to elucidate the effect of SOCS on psoriasis because of the complex pathogenesis of this disease." (PMID 36169255, 2022). "Compared to the control group, the expression of SOCS1 and SOCS3 in psoriasis mice was significantly decreased (p < .05)." (PMID 36444619, 2022). "It was proposed that increased miR-203 expression in psoriasis lesions is correlated with diminished cytokine-signaling 3 (SOCS3) suppression and a resulting rise in the transcription factor (STAT-3), which is closely linked to the development of psoriasis." (PMID 36341243, 2022). "Similarly to SOCS1, SOCS3 is also upregulated in psoriasis epidermis, especially in areas close to CD3+ dermal infiltrate likely producing inflammatory cytokines." (PMID 38975347, 2024). "Therefore, SOCS3 can be seen to affect and protect against the harmful effects of prolonged proinflammatory signaling in psoriasis." (PMID 36169255, 2022). "Additionally, etanercept inhibited the activation of JAK/STAT3 signaling pathway and promoted the protein expression of SOCS1 and SOCS3 in psoriasis mice." (PMID 36444619, 2022). "We conducted this study to evaluate miR-203 expression level in the plasma of psoriasis patients to investigate its role and target genes SOCS3, SOCS6, P63, TNF-α, IL-8, and IL-24 in the systemic pathogenesis of this disease and correlate these data with the disease course." (PMID 36341243, 2022). "MiR-203 is a key factor in psoriasis since it could regulate SOCS3 and lead to the activation of STAT3, hence controlling the proliferation and differentiation of ESCs in skin development and wound healing through P63 and Zfp281." (PMID 32787903, 2020). "SOCS-3 negatively regulates the activation of the transcription factor signal transducer and activator of transcription 3 (STAT-3), which is indeed overly active in psoriasis and implicated in cytokine signaling." (PMID 20594301, 2010). "However, this study was done in murine keratinocytes and under non-inflammatory conditions, and, thus, it is still possible that miR-203 targets SOCS-3 in human keratinocytes during inflammatory conditions like psoriasis." (PMID 20594301, 2010). "Therefore, experimentally mimicked SOCS3 overexpression might turn out to be beneficial in psoriasis by reducing STAT3-dependent inflammation and proliferation." (PMID 38975347, 2024). "SOCS1 and SOCS3 expression is reduced in tumor lesions of BCC and SCC, as compared to other skin inflammatory conditions such as psoriasis, despite the high number of IL-22-secreting tumor-infiltrating lymphocytes." (PMID 38975347, 2024).
psoriasis (continued). "This work evaluated the expression levels of the circulating miR-203 target genes SOCS3, SOCS6, TP63, TNF-, IL8, and IL24 in psoriasis patients." (PMID 36341243, 2022). "In order to gain a better knowledge of miRNAs role in the disease, the current study looked into the influence of miR-203 expression and its target genes SOCS3, SOCS6, TP63, TNF-α, IL-8, and IL-24 on the pathogenesis and clinical course of psoriasis." (PMID 36341243, 2022). "We found that SOCS3 and SOCS1 expression was reduced in vivo, in tumor lesions of BCC and SCC, as compared to other skin inflammatory conditions such as psoriasis, despite the high number of IL-22-secreting TILs." (PMID 28445952, 2017). "The polymorphisms of SOCS3 rs4969169 and SOCS7 rs3748726 were found to have no effective role in the pathogenesis of psoriasis." (PMID 36169255, 2022). "Besides, STAT3 transgenic mice and SOCS3 knockout mice (the negative regulator of STAT3) have constitutive activation of STAT3 and both develop murine IL-6-driven psoriasis." (PMID 26136626, 2015). "A study showed that miR-203 could inhibit the expression of SOCS3 by directly binding to the 3’-UTR of SOCS3 and promoted the degradation of SOCS3 mRNA, thereby activating the JAK2/STAT3 signaling pathway to promote the progression of psoriasis." (PMID 36618400, 2022). "However, the activation of SOCS1 and SOCS3 appears inadequate to completely inhibit the expression of STAT-downstream targets in psoriasis, making this negative circuit nonfunctional in the context of psoriasis, and it was, therefore, removed from the model." (PMID 34877506, 2021). "miR-203 was found to be up-regulated in psoriasis and computational predictions suggested that miR-203 targets SOCS-3 via an evolutionarily conserved 10-nucleotide sequence that includes the entire seed region and carries perfect complementarity with SOCS-3 mRNA." (PMID 20594301, 2010). "Thus, up-regulated miR-203 in psoriasis might have important implications for psoriasis pathogenesis by preventing the up-regulation and negative feedback mechanism of SOCS-3 on cytokine signaling." (PMID 20594301, 2010). "Neither JAK2 phosphorylation nor SOCS1 and SOCS3 expression was affected by HCA, suggesting that HCA-mediated suppression of PKM2-STAT3 signaling is a key event in the attenuation of psoriasis development." (PMID 33990689, 2021).
gastric cancer (16 papers, 2010 to 2025). A primary or metastatic malignant neoplasm involving the stomach. "In conclusion, we clarified that an oHSV armed with SOCS3 enhanced the viral replication and oncolysis in human gastric cancer cells, and that the combined effect of SOCS3 with oHSVs inhibited human gastric cancer specimen proliferation ex vivo." (PMID 33659045, 2021). "On the other hand, the expression of SOCS3 in MKN1 gastric cancer cells was suppressed by T-01 infection." (PMID 33659045, 2021). "Downregulation of miR-340 inhibited gastric cancer cell proliferation, arrested the cell cycle, and facilitated apoptosis by upregulating SOCS3 to suppress the JAK-STAT3 signaling pathway." (PMID 32273831, 2020). "As discussed, we focused on SOCS3, and generated a new type of oHSVs expressing SOCS3 (T-SOCS3) and compared the third-generation type of oHSV (T-01) with T-SOCS3 in antitumor effect for human gastric cancer cells." (PMID 33659045, 2021). "Armed oncolytic HSVs expressing SOCS3 may be an efficacious therapeutic agent for gastric cancer treatment." (PMID 33659045, 2021). "SOCS3 expression was detected in human gastric cancer cell line (MKN1, MKN28, and MNK73)." (PMID 33659045, 2021). "Here, we focus on SOCS3 for oncolytic virotherapy using HSV for gastric cancer." (PMID 33659045, 2021). "We hypothesized that oHSVs expressing SOCS3 can effectively replicate and destroy within gastric cancer cells." (PMID 33659045, 2021). "However, SOCS3 may have a stimulative effect on tumors, including gastric cancer and renal cell carcinoma." (PMID 36690663, 2023). "To treat gastric cancer, we generated and evaluated the efficacy of an attractive type of oncolytic HSV expressing the suppressor of cytokine signaling 3 (SOCS3)." (PMID 33659045, 2021). "In fact, mice with knock-in mutation located at Y757F on gp130, which destroys the docking site for SOCS3 that negatively regulates STAT3 activation, develop antral gastric cancer." (PMID 26186918, 2015). "The gp130F/F mutation impairs SOCS3-mediated negative feedback of STAT3 signaling, leading to hyperactivation of the IL-6/STAT3 pathway that is frequently dysregulated in human gastric cancer." (PMID 40673273, 2025). "Deletion of the suppressor of cytokine signaling 3 (SOCS3) gene and activation of the JAK-STAT signaling pathway are closely related to hepatocarcinogenesis, gastric cancer, malignant fibrous histiocytoma, as well as the occurrence, development and metastasis of EOC." (PMID 32516133, 2020). "Due to the lack of investigation, we plan on exploring SOCS3 as a future topic for the discovery of new therapeutic options for gastric cancer." (PMID 31130822, 2019). "This gp130Y757F mutation impairs SOCS3-mediated negative feedback regulation, leading to hyperactivation of the IL-6/JAK/STAT3 pathway, which is one of the most frequently dysregulated signaling cascades in human gastric cancer and is associated with inflammation, proliferation, and immune evasion." (PMID 40673273, 2025).
allergic disease (14 papers, 2004 to 2025). An immune response that occurs following re-exposure to an innocuous antigen, and that requires the presence of existing antibodies against that antigen. "SOCS3 expression in T-cells inhibits Th1 development and promotes Th2 responses, increasing the risk for Th2-mediated allergic diseases, including AD." (PMID 35889539, 2022). "Despite of being the low producing genotype, CC, had relatively increased SOCS3 levels but the OR value established its role as a risk genotype for allergy." (PMID 31251775, 2019). "Moreover, the association between GG and SOCS3 expression implied that SOCS3 expression is firmly regulated by IL-6 serum levels thereby making IL-6 as a potential candidate involved in the prognosis and pathogenesis of allergy." (PMID 31251775, 2019). "If TLR2 expression is merely the result of exposure to pathogens, and low SOCS-3 expression is associated with protection from allergy, it would be of interest to know whether SOCS-3 is also lower in the European farmers' environment despite a higher TLR2 expression." (PMID 18414649, 2008). "Such reciprocal inhibition between SOCS3 (Th2-associated) and SOCS5 (Th1-associated) underpins the Th1/Th2 imbalance observed in allergic diseases." (PMID 40568590, 2025). "SOCS3 is a proinflammatory regulator in the pathogenesis of various autoimmune and inflammatory diseases, including allergic diseases and inflammatory bowel disease." (PMID 40104138, 2025). "SOCS3 plays a regulatory role in a variety of allergic diseases, and the severity of allergic diseases is closely related to its selective expression in Th2 cells: a high expression of SOCS3 drives Th cells to differentiate into Th2 cells." (PMID 39057037, 2024). "SOCS3 has an important role in regulating Th2 responses in allergic disease, and inhibiting its expression alleviates allergic inflammation." (PMID 36434595, 2022). "Experiments have shown that miR-30a-5p can regulate the occurrence and development of allergic disease by targeting the inhibition of SOCS3 expression." (PMID 32273831, 2020). "The binding of IL-6 to receptor initiates downstream signaling of SOCS3, the auto-inhibitor of IL-6, has been widely studied in allergy." (PMID 31251775, 2019). "SOCS3 has been evaluated for its role in the prognosis of allergy and other inflammatory conditions." (PMID 31251775, 2019). "Allergy is a gender biased condition and is known to affect females more than male so we further analyzed the levels of SOCS3 in male and female atopic cases to establish a molecular basis for the claim." (PMID 31251775, 2019). "The given study focuses on the assessment of crosstalk between SOCS3 and IL-6 to unravel the molecular significance of SOCS3 and IL-6 in the diagnosis and prognosis of allergy." (PMID 31251775, 2019). "The results signified the role of SOCS3 in allergic reaction as it was elevated in different types of allergies under the influence of IL-6 serum levels." (PMID 31251775, 2019). "The elevated SOCS3 levels in females with atopic condition make it an important prognostic marker for allergy." (PMID 31251775, 2019). "SOCS1 is commonly silenced in inflammatory diseases, and over-expression of SOCS3 correlates with allergies." (PMID 26090929, 2015). "A further allergic disease was also characterized to have an expression level of SOCS-3 contrary to the presently identified COPD profile." (PMID 24138793, 2013). "Because SOCS3 is involved in the regulation of the Th1/Th2 axis in allergic diseases, we measured the SOCS3 mRNA expression in bronchial biopsies from healthy controls, asthmatics, and NAEB subjects." (PMID 21765854, 2011). "Elegant studies by Kubo and co workers in animal models have shown SOCS-3 to be involved in regulation of immune responses in allergic disease." (PMID 18414649, 2008).
allergic disease (continued). "Consistent with this notion, PB T cells from patients with allergic diseases significantly express high levels of SOCS3 transcripts, and the SOCS3 expression correlates well with serum IgE levels and disease pathology." (PMID 15535835, 2004). "In allergic diseases, the upregulation of SOCS3 may be a self-protection mechanism of the body against excessive inflammatory responses." (PMID 40568590, 2025). "The variation in the SOCS3 expression in different types of allergies and the expression difference between male and female establish it as a reliable candidate for biomarker to determine the prognosis of allergy." (PMID 31251775, 2019). "This up-regulation of SOCS3 provides insight to the prognosis of allergy." (PMID 31251775, 2019). "Notably, the study established SOCS3 and IL-6 as potential targets for the diagnosis/prognosis of allergy and for the development of reliable therapeutic strategies to control atopic conditions in the near future." (PMID 31251775, 2019). "SOCS3 is known to mediate allergic response through Th2 activity while its attenuation aggravates the allergic conditions thus, establishing its protective role against allergic reaction." (PMID 31251775, 2019). "Moreover, studies depicting the variation in SOCS3 expression in different atopic cases indicated the progression of allergy when SOCS3 molecule is unable to produce its effect." (PMID 31251775, 2019). "Furthermore, the polymorphic study of IL-6 promoter region (IL-6 174-G/C) in atopic population has reasserted the importance of SOCS3 and IL-6 in the diagnosis and prognosis of allergy." (PMID 31251775, 2019). "Nevertheless, SOCS3 expression levels are high in T cells from patients with this allergic disease." (PMID 21547260, 2011). "Accordingly, one of the new models of therapy for allergic diseases could entail targeting SOCS3 by using a Gal-3 gene therapy approach via inhibition of Th2 response." (PMID 21547260, 2011). "In addition, some studies suggest that SOCS-3 and its ligases may become new targets for the development of allergy-related therapeutic drugs." (PMID 39057037, 2024). "It is worth noting that although SOCS3 is considered to be mainly expressed in Th2 cells and can inhibit Th1-type immune responses, its specific functions in allergic diseases, especially AR, are not completely clear." (PMID 40568590, 2025). "Larger epidemiological studies will be needed to be able to test this hypothesis directly and to confirm that helminths modify the development of allergy by modulating the expression levels of TLR2 and SOCS-3." (PMID 18414649, 2008).